ENSG00000199571
Synonyms: LOC124900327
Gene: Small nucleolar RNA gene on chromosome 12 (39,819,750 to 39,819,883, reverse strand). Ensembl gene ENSG00000199571.
Gene Ontology:
Biological process: RNA processing
Cellular component: nucleolus
Homologues: Orthologues: rat LOC120098365 (78% identical). Paralogues in human: SNORA22 (88% identical), SNORA22B (88% identical), SNORA22C (88% identical).